TRAT1 (T cell receptor associated transmembrane adaptor 1)
Description:
Stabilizes the TCR (T-cell antigen receptor)/CD3 complex at the surface of T-cells.
Synonyms: TRIM; TCRIM; HSPC062; pp29/30
Tractability: Antibody: UniProt places it where antibodies can reach, with high confidence; its Gene Ontology location is reachable by antibodies, with high confidence; UniProt predicts a signal peptide or a membrane-spanning region; the Human Protein Atlas places it where antibodies can reach. PROTAC: ubiquitination databases record sites on it.
Gene: Protein-coding gene on chromosome 3 (108,822,770 to 108,855,005, forward strand). Ensembl gene ENSG00000163519.
Subcellular location: Cell membrane
Subcellular location (Human Protein Atlas): Plasma membrane; Centriolar satellite; Mitotic spindle
Pathways (Reactome):
Signal Transduction: PI5P, PP2A and IER3 Regulate PI3K/AKT Signaling; PIP3 activates AKT signaling
Disease: Constitutive Signaling by Aberrant PI3K in Cancer
Immune System: Downstream TCR signaling
Gene Ontology:
Molecular function: protein binding; transmembrane receptor protein tyrosine kinase adaptor activity
Biological process: negative regulation of receptor recycling; negative regulation of transport; positive regulation of calcium-mediated signaling; positive regulation of T cell receptor signaling pathway; cellular defense response; signal transduction; cell surface receptor protein tyrosine kinase signaling pathway
Cellular component: centriolar satellite; plasma membrane; T cell receptor complex
Genetic constraint (gnomAD): Loss-of-function variants: 7 observed, 7.09 expected, observed/expected ratio (o/e) 0.99, 90% interval 0.56 to 1.73. That is too few expected variants to judge how well the gene tolerates losing a copy. Missense variants: 184 observed, 181.9 expected, observed/expected ratio (o/e) 1.01, 90% interval 0.9 to 1.14. Synonymous variants: 61 observed, 63.32 expected, observed/expected ratio (o/e) 0.96, 90% interval 0.78 to 1.19.
Homologues: Orthologues: chimpanzee TRAT1 (99% identical), macaque TRAT1 (94% identical), rabbit TRAT1 (80% identical), guinea pig TRAT1 (74% identical), dog TRAT1 (70% identical), mouse Trat1 (70% identical), rat Trat1 (68% identical), pig TRAT1 (66% identical).
Diseases named in the same sentence as TRAT1 in open-access papers:
TRAT1 is named in the same sentence as 61 diseases in open-access papers, as found by Europe PMC text mining. Sharing a sentence is not in itself a finding about the gene and the disease. The quoted sentences say what the papers report.
breast cancer (6 papers, 2009 to 2025). A primary or metastatic malignant neoplasm involving the breast. "TRAT1 is the T-cell receptor-associated transmembrane adaptor, and it has been confirmed to be upregulated in T cells of breast cancer in the previous study." (PMID 36479102, 2022). "PTTG2 has been implicated in glioblastoma tumorigenesis as well as in head and neck squamous cell carcinoma, UTS2 has been reported to possess prognostic value in colorectal and breast cancers, TRAT1 in early breast cancer prognosis and DUSP1 in sarcoma progression." (PMID 39478658, 2025).
ovarian carcinoma (4 papers, 2015 to 2023). A malignant neoplasm originating from the surface ovarian epithelium. "Except for CD8B, TRAT1 and SYK, all the other module genes were found to be significantly associated with survival of ovarian cancer patients (p < 0.05)." (PMID 26099452, 2015). "In certain cancer types, different eQTL-lncRNAs pairs influence the same set of mRNA targets; for example, in ovarian cancer, two eQTL (2p25.2 and 7q34) eventually regulate the same set of mRNAs (FASLG, GZMM, PYHIN1 and TRAT1) but through different elncRNAs (AC092580.4 and TRBV11-2)." (PMID 33194770, 2020).
atherosclerosis (2 papers, 2023). A disease characterized by the build-up of fatty material and calcium deposition in the arterial wall resulting in partial or complete occlusion of the arterial lumen. "Similarly, the expression levels of CD28, TRAT1, TRAV13-1, and LEF1 were related to smoking and smoking-related atherosclerosis." (PMID 37762221, 2023).
Hypertension (2 papers, 2014 to 2019). The presence of chronic increased pressure in the systemic arterial system. "TRAT1 and DHX8 have little exposure in the literature related to hypertension or related outcomes." (PMID 25519321, 2014).
lung adenocarcinoma (2 papers, 2022 to 2025). A carcinoma that arises from the lung and is characterized by the presence of malignant glandular epithelial cells. "The roles and mechanisms of T-cell receptor (TCR)-associated transmembrane adaptor 1 (TRAT1) in lung adenocarcinoma (LAC) have not yet been reported in the relevant literature." (PMID 36276113, 2022).
T cell lymphomas (2 papers, 2015 to 2023). "The dysregulation of the mTORC2 pathway is further validated by the observed down-regulation of TCR components (TRAC, TRBC1) and stabilizing molecules (TRAT1) seen across multiple T-cell lymphoma subtypes." (PMID 26566034, 2015). "However, in T cell lymphomas, TRAT1 can be highly expressed in tumor cells." (PMID 38026637, 2023).
thyroid cancer (2 papers, 2022 to 2025). "Subsequently, TCGA database results showed the expression of CXCL10, CD40LG, KRT14, TRAT1, and TREM2, with only TREM2 expression levels being upregulated in thyroid cancer." (PMID 36438899, 2022). "Subsequently, the TCGA database results showed the expression of CXCL10, CD40LG, KRT14, TRAT1, and TREM2, with only TREM2 expression levels being upregulated in thyroid cancer (P < 0.05)." (PMID 36438899, 2022).
Allergy (1 paper, 2021). An allergy is an immune response or reaction to substances that are usually not harmful. "TRAT1 was hypomethylated in the Lω group, whereas it was hypermethylated in the independent allergy data set, making it tempting to speculate that the combined intervention may enable proper T cell signalling propagation into the cell." (PMID 34193262, 2021). "Comparing the direction of methylation to the independent allergy data set, four genes exhibited the opposite direction of patterning (HIVEP3, TRAT1, BCL7A and SLC442A), while the DNA methylation patterning of the remaining genes were identical between the groups." (PMID 34193262, 2021).
dilated cardiomyopathy (1 paper, 2025). Cardiomyopathy which is characterized by dilation and contractile dysfunction of the left and right ventricles. "TRAT1 was involved in ribosome biogenesis and cardiac-related pathways such as dilated cardiomyopathy, whereas ANKRD20A1 was associated with gene replication and cell cycle-related processes, highlighting its potential role in transcriptional regulation in HCM." (PMID 41200169, 2025).
discoid lupus erythematosus (1 paper, 2024). A chronic, autoimmune skin condition that manifests with a red, scaling rash, most often found on the face, ears, and scalp; these lesions often lead to permanent scarring and dyspigmentation. "Among the uniquely expressed genes in each disease, we observed significantly expressed IFNG in Discoid Lupus Erythematosus, TRAT1 in Epitheliotropic Lymphoma, and CXCL8 and CSF3R in pemphigus affected dogs." (PMID 39911479, 2024).
metastatic melanoma (1 paper, 2021). A melanoma that has spread from its primary site to another anatomic site. "TRAT1 encodes the tripartite motif (TRIM) protein which is essential for T-cell activation and positively correlated with the survival of patients with metastatic melanoma." (PMID 34733790, 2021).
pemphigus (1 paper, 2024). Pemphigus is a group of rare autoimmune diseases that cause blistering of the skin and mucous membranes (mouth, nose, throat, eyes, and genitals).This conditioncan occur at any age, but often strikes people in middle or older age. "Specifically, we noted a unique expression of IFNG in DLE (p = 0.0213), a unique expression of TRAT1 and FOXO3A in EL patients (p < 0.0001 and p < 0.0001), and CXCL8 and CSF3R in pemphigus patients (p = 0.0002 and p = 0.0016)." (PMID 39911479, 2024).
systemic lupus erythematosus (1 paper, 2025). An autoimmune multi-organ disease typically associated with vasculopathy and autoantibody production. "TRAT1 shared several overlapping pathways with SYDE2, while ANKRD20A1 primarily affected DNA replication, transcription factor activity, and systemic lupus erythematosus-related processes." (PMID 41200169, 2025).
tumor (23 papers, 2009 to 2025). "TRAT1 (TCR-related transmembrane junction 1) is a key TCR regulatory gene associated with tumor progression." (PMID 37266435, 2023). "The relationship between TRAT1 expression levels and PD-L1 expression, tumour mutational burden (TMB), response efficacy, and other immune characteristics in LAC cells was also obtained from the cBioPortal database." (PMID 36276113, 2022). "This suggests that TRAT1 functions as a tumour suppressor in LAC progression to inhibit cancer growth and migration." (PMID 36276113, 2022). "What is more, there were higher expressions of FCRL3, IFNG, and TRAT1 in recurrent tumor(n = 5) compared with primary tumor(n = 371)." (PMID 34868239, 2021). "Gene intersection and survival analysis showed that there were 435 DEG crosses in PTC patients and genome-wide tumor samples, only CXCL10, CD40LG, KRT14, TRAT1, and TREM2 were associated with patient prognosis, and TCGA showed that only the TREM2 expression was upregulated in PTC." (PMID 36438899, 2022). "This suggests that TRAT1 may be involved in cell growth and migration as a tumour suppressor gene in LAC." (PMID 36276113, 2022). "For patients diagnosed with EL, TRAT1, a T cell-specific gene, could be a promising treatment avenue as this gene was found to be uniquely expressed and significantly upregulated in this disorder, which makes sense given the tumor is T cell-derived." (PMID 39911479, 2024).
cancer (22 papers, 2008 to 2025). A tumor composed of atypical neoplastic, often pleomorphic cells that invade other tissues. "Abnormal expression of TRAT1 is associated with cancer mechanisms and immunity, indicating that TRAT1 has an important role in LAC progression." (PMID 36276113, 2022). "Our previous study found that the expression levels of TRAT1 in NSCLC, LAC, and LUSC tissues were significantly decreased, and the decreased expression level of TRAT1 was associated with poor prognosis in patients with cancer." (PMID 36276113, 2022). "In addition, the elevated expression of TRAT1 is associated with cancer signalling pathways such as Toll-like receptor, VEGF, and MAPK pathways, which should be further confirmed by western blotting in the future." (PMID 36276113, 2022). "T cell receptor (TCR)-associated transmembrane adaptor 1 (TRAT1) is one of the hub regulatory genes of TCR and is associated with cancer progression." (PMID 36276113, 2022). "In addition, TRAT1 co-expressed genes were involved in Th1, Th2, and Th17 cell differentiation; PD-L1 expression and PD-1 checkpoint pathway in cancer; TCR, B cell receptor (BCR), NF-kappa B, JAK-STAT, PI3K-AKT, VEGF, and other signalling pathways as per KEGG analysis." (PMID 36276113, 2022). "All three genes (i.e., TRAT1, POGZ, and FMN1) have been identified as potential therapeutic targets for the treatment of some cancers." (PMID 38396979, 2024). "In conclusions, TRAT1 overexpression inhibited the growth and migration of LAC cells, thereby delaying cancer progression, and was correlated with the LAC microenvironment and RNA modifications." (PMID 36276113, 2022). "The expression of TRAT1 was activated in LAC cells, and the roles of TRAT1 overexpression in the growth and migration of cancer cells was investigated using flow cytometry, Cell Counting Kit-8 (CCK-8), and migration and invasion assays." (PMID 36276113, 2022). "However, the roles of TRAT1 overexpression and the Toll-like receptor, VEGF, MAPK, and other cancer signalling pathways need to be further confirmed in our models via western blotting." (PMID 36276113, 2022). "The shortcomings of our study were the lack of LAC tissue specimens, which resulted in us not able to confirm the expression of TRAT1 in LAC tissues and the relationship between the expression levels of TRAT1 and prognosis of patients with cancer, which needs to be verified in the future." (PMID 36276113, 2022).
blood cancers (1 paper, 2023). "In non-blood cancers (solid tumors), TRAT1 expression is important for a good prognosis." (PMID 38026637, 2023).
TRAT1 also shares sentences with these, for which no sentence is quoted: viral infection (24 papers); infection (20); HIV-1 infection (8); autoimmune disease (6); hepatocellular carcinoma (3); infectious disease (3); brain tumor (2); colon cancer (2); genetic diseases (2); glioblastoma (2); glioma (2); melanoma (2); Sepsis (2); Sjögren's syndrome (2); adrenocortical carcinoma (1); Anxiety (1); arbovirus infection (1); bacterial infections (1); colorectal carcinoma (1); COVID-19 (1); diabetes mellitus (1); familial Mediterranean fever (1); head and neck squamous cell carcinoma (1); hepatoblastoma (1); immune diseases (1); inflammatory bowel disease (1); kidney cancer (1); measles (1); mental health diseases (1); muscular dystrophy (1).
A further 15 diseases each share a sentence with TRAT1 in 1 paper.